PGP (phosphoglycolate phosphatase)
Description:
Phosphatase with activity against multiple substrates. Acts as a metabolite repair enzyme which eliminates toxic glycolytic side products. Dephosphorylates 2-phosphoglycolate which is generated during the repair of oxidative DNA lesions. This controls triosephosphate isomerase activity, glycerolipid partitioning and cell proliferation in the embryo and is required for embryonic development (By similarity). Dephosphorylates 4-phosphoerythronate, a side product which is produced by GAPDH and which inhibits 6-phosphogluconate dehydrogenase. Dephosphorylation of 4-phosphoerythronate prevents the accumulation of high 4-phosphoerythronate levels which would otherwise inhibit the pentose phosphate pathway. Dephosphorylates 2-phospho-L-lactate which is a product of a pyruvate kinase side reaction. This prevents the inhibition of fructose-2,6-bisphosphate production and allows glycolysis to occur. Has glycerol-3-phosphate phosphatase activity, hydrolyzing glycerol-3-phosphate into glycerol and thereby regulating the cellular levels of glycerol-3-phosphate, a metabolic intermediate of glucose, lipid and energy metabolism. Has been shown to have tyrosine-protein phosphatase activity although the physiological relevance is unclear. In vitro, has phosphatase activity toward ADP, ATP, GDP and GTP (By similarity).
Synonyms: AUM; G3PP; PGPase
Tractability: PROTAC: ubiquitination databases record sites on it; its protein half-life has been measured.
Target class: Enzyme; Hydrolase
Gene: Protein-coding gene on chromosome 16 (2,211,593 to 2,214,840, reverse strand). Ensembl gene ENSG00000184207.
Subcellular location (Human Protein Atlas): Nuclear bodies
Pathways (Reactome):
Metabolism: Glycerophospholipid biosynthesis
Gene Ontology:
Molecular function: phosphoglycolate phosphatase activity; sn-glycerol 1-phosphatase activity; sn-glycerol 3-phosphatase activity; magnesium ion binding; protein tyrosine phosphatase activity; ADP phosphatase activity; phosphatase activity
Biological process: glycerol biosynthetic process; glycerophospholipid metabolic process; negative regulation of gluconeogenesis; toxic metabolite repair
Cellular component: cytosol
Genetic constraint (gnomAD): Loss-of-function variants: 9 observed, 14.16 expected, observed/expected ratio (o/e) 0.64, 90% interval 0.38 to 1.11. The synonymous counts are far from expectation, so gnomAD's model fits this gene poorly and the ratio says little. Missense variants: 385 observed, 344.83 expected, observed/expected ratio (o/e) 1.12, 90% interval 1.03 to 1.22. Synonymous variants: 290 observed, 181.31 expected, observed/expected ratio (o/e) 1.6, 90% interval 1.45 to 1.76.
Homologues: Orthologues: chimpanzee PGP (99% identical), macaque PGP (98% identical), dog PGP (94% identical), guinea pig PGP (92% identical), mouse Pgp (91% identical), rat Pgp (90% identical), pig PGP (76% identical), tropical clawed frog pgp (55% identical), zebrafish pgp (55% identical), Drosophila melanogaster CG5567 (39% identical), Caenorhabditis elegans pgph-2 (34% identical), Caenorhabditis elegans pgph-1 (34% identical), and 9 more. Paralogues in human: PDXP (42% identical), LHPP (25% identical), HDHD2 (24% identical).
Diseases named in the same sentence as PGP in open-access papers:
PGP is named in the same sentence as 366 diseases in open-access papers, as found by Europe PMC text mining. Sharing a sentence is not in itself a finding about the gene and the disease. The quoted sentences say what the papers report.
breast carcinoma (329 papers, 1990 to 2026). "We examined a handful of CSC markers commonly associated with breast cancer (ALDH1A1, ABCG2, PGP, FUT4)." (PMID 34579762, 2021). "The most important in breast cancer are: PGP (P-glycoprotein), BCRP (Brest Cancer Resistance Protein), MRP1 (Multridrug resistance Protein 1) and MRP3 (Multidrug Resistance Protein 3)." (PMID 23773525, 2013). "Breast cancer spheroids (BT474, HCC1954, EFM192A) were more resistant to the drugs neratinib and docetaxel, due to the increase in both CYP3A4 activity and the expression of two membrane transporters associated with resistance (PGP and BCRP)." (PMID 38201092, 2023). "In the treatment of breast cancer, β-elemene mediates MDR-related miR-34a and miR-452 in cells and regulates the expression of target genes PTEN and PGP, reducing chemoresistance transmission through exosomes and reversing drug resistance in breast cancer cells." (PMID 36203417, 2022). "Biotin-functionalized NPs made from PLGA-PEI copolymers were used to deliver phosphoglycolate phosphatase (PGP) siRNA and paclitaxel (PTX) to mammary cancer cells." (PMID 35586474, 2022). "That has become the aim of our study, to assess the expression of PGP, BCRP, MRP1 and MRP3 in canine mammary cancer cell lines and to investigate their role in cancer resistance to vinblastine, cisplatin and cyclophosphamide with using RNAi approach." (PMID 23773525, 2013). "That is why the aim of our study was to assess expression of four the most important efflux pumps: PGP, BCRP, MRP1 and MRP3 in canine mammary cancer cells as well as to investigate their role in resistance to: cisplatin, cyclophosphamide and vinblastine." (PMID 23773525, 2013). "That is why the aim of our study was to assess expression of PGP, BCRP, MRP1 and MRP3 in five canine mammary cancer cell lines and to investigate their role in cancer resistance to vinblastine, cisplatin and cyclophosphamide which are used in breast cancer treatment." (PMID 23773525, 2013). "The results suggested that in canine mammary cancer, the vinblastine efflux was mediated by PGP and MRP1 proteins, cisplatin efflux was mediated by all four examined efflux pumps (PGP, BCRP, MRP1 and MRP3), whereas cyclophosphamide resistance was related to BCRP activity." (PMID 23773525, 2013).
colon carcinoma (78 papers, 2002 to 2025). "Antitumor effect of SBT-1214 delivered i.v. to SCID mice bearing PgP+ DLD-1 human colon tumor xenografts." (PMID 20630067, 2010). "We also evaluated the levels of CD133, a colon cancer stem cell marker that tends to accumulate in cell protrusions, and ABCB1/P-glycoprotein (PgP), which pumps out various anticancer drugs including DXR." (PMID 28094304, 2017).
epilepsy (70 papers, 2011 to 2026). A brain disorder characterized by episodes of abnormally increased neuronal discharge resulting in transient episodes of sensory or motor neurological dysfunction, or psychic dysfunction. "The PgP inhibitor, tariquidar, has successfully rescued drug sensitivity in PB-resistant rats with epilepsy, directly supporting the transporter hypothesis." (PMID 36902275, 2023).
colorectal cancer (64 papers, 2011 to 2025). A primary or metastatic malignant neoplasm that affects the colon or rectum. "Here, we measured phosphoglycolate concentrations in PGP knockout cell lines derived from the HCT116 colorectal cancer and U2OS osteosarcoma cell lines, which were cultured either in the presence or absence of glycolate, a potential biosynthetic precursor of glycolate." (PMID 30670572, 2019). "To test this, we treated PGP knockout lines obtained from the HCT116 colorectal carcinoma and U2OS osteosarcoma cell line with Bleomycin, the chemotherapeutic agent that is best characterized to lead to the production of phosphoglycolate, and with ionizing radiation." (PMID 30670572, 2019). "And U0126 (MEK inhibitor) promoted PGP protein degradation in colorectal cancer was also reported." (PMID 23320839, 2013).
glioma (46 papers, 1996 to 2025). A benign or malignant brain and spinal cord tumor that arises from glial cells (astrocytes, oligodendrocytes, ependymal cells). "In this study, we evaluated PgP as a gene carrier and demonstrate that PgP can efficiently deliver reporter genes, pGFP in rat glioma (C6) cells in vitro, and pβ-gal in a rat T5 SCT model in vivo." (PMID 30965667, 2019). "In this study, we evaluated PgP as a gene carrier in glioma (C6) cells in vitro using reporter genes such as pGFP and a rat spinal cord tumor model in vivo using reporter gen, pβ-Gal, and therapeutic gene, pHSV-TK." (PMID 30965667, 2019).
acute myeloid leukemia (40 papers, 1997 to 2025). Acute myeloid leukemia (AML) is a group of neoplasms arising from precursor cells committed to the myeloid cell-line differentiation. "With respect to Sia modifications, prior studies have reported a positive correlation between Sialyl transferases, ST3Gal5 and ST8Sia4 expression and efflux proteins, PgP and MRP1 expression in human acute myeloid leukemia." (PMID 37377914, 2023).
osteosarcoma (39 papers, 1998 to 2025). A usually aggressive malignant bone-forming mesenchymal neoplasm, predominantly affecting adolescents and young adults. "Nevertheless, some controversy remains, and further investigations are needed to confirm the role of PgP as a risk stratification variable in newly diagnosed osteosarcoma." (PMID 40667646, 2025). "The controversy regarding the role of immunohistochemical staining for assessing PgP expression in osteosarcoma has been discussed elsewhere." (PMID 40667646, 2025). "The multidrug-resistant phenotype was partially reverted in-vitro by the PgP inhibitor verapamil, as shown in other osteosarcoma resistant lines with other PgP inhibitors." (PMID 31319571, 2019). "A third of osteosarcoma patients expressed PgP at diagnosis." (PMID 31319571, 2019). "Another potential weaker PgP inhibitor and studied in osteosarcoma relapse treatment (NCT02243605), the multi-tyrosine kinase inhibitor cabozantinib, did not revert PgP phenotype when used at a dose that did not inhibit cell proliferation, conversely to what was shown in hepatoblastoma cells." (PMID 31319571, 2019).
neuroblastoma (23 papers, 1991 to 2025). Neuroblastoma (NB) is the most common solid, extracranial childhood tumor. "In addition, we observed that L1 neural cell adhesion molecule conjugated PgP (L1-PgP) efficiently delivered NANP-siRhoA in cultured neuroblastoma (B35) cells." (PMID 40308740, 2024).
cervical carcinoma (20 papers, 2012 to 2025). A carcinoma arising from either the exocervical squamous epithelium or the endocervical glandular epithelium. "It was shown that the reconstitution of the miR-7-5p level resulted in the decreased expression of PGP, BCRP, MRP1 and MRP6 encoding genes in GB-derived (A172 and T98G), cervical carcinoma-derived HeLa and PTC-derived TPC-1 cells." (PMID 32708846, 2020).
diabetes (20 papers, 2010 to 2025). "Antibodies against PgP 9.5 are being used as the main diagnostic tool of small fiber neuropathy (SFN), which can be associated with pre-diabetes status." (PMID 32927766, 2020).
Parkinson disease (15 papers, 2009 to 2025). A progressive degenerative disorder of the central nervous system characterized by loss of dopamine producing neurons in the substantia nigra and the presence of Lewy bodies in the substantia nigra and locus coeruleus. "Polymorphisms in the Abcb1 gene have been recognized in Parkinson's disease patients, and PET studies have shown decreased function of PGP in Parkinson's disease." (PMID 23986663, 2013).
colon adenocarcinoma (14 papers, 2013 to 2023). "An in vitro study, for instance, revealed that lipid-based additives such as Peceol and Gelucire 44/14, both approved as GRAS, inhibit the PgP-mediated efflux in human colon adenocarcinoma cells (Caco-2) by decreasing the PgP-protein expression." (PMID 25788447, 2015).
liver cancer (11 papers, 2012 to 2025). An epithelial or non-epithelial malignant neoplasm that arises from the liver. "Our in vitro experiments on ABCB1 and PGP expression utilized HepG2, an established cell line of human liver cancer origin." (PMID 36904118, 2023).
depression (10 papers, 2010 to 2025). "Furthermore, HPA hyperactivity during depression alters the blood brain barrier by deregulation of the multidrug resistance p-glycoprotein (MRD PGP)." (PMID 21087475, 2010).
Cryptosporidium infection (2 papers, 2018 to 2019). "To explore the underlying mechanism, we detected the submucosal nerve plexus of the jejunal tissue, intestinal intramuscular plexus and villus nerve fibers post Cryptosporidium infection (The nerve cells were labeled in 5 μm sections with a monoclonal mouse PGP 9.5 antibody)." (PMID 29522573, 2018).
medulloblastoma (2 papers, 2018 to 2020). A malignant, invasive embryonal neoplasm arising from the cerebellum. "PGP expression was only found in pediatric medulloblastoma cases." (PMID 29869738, 2018).
psoriasis (2 papers, 2018). An autoimmune condition characterized by red, well-delineated plaques with silvery scales that are usually on the extensor surfaces and scalp. "Using siRNA technique, UCHL1/PGP 9.5-expressing cell lines showed more than 200 downregulated and comparable number of upregulated genes engaged in most cellular processes, also those responsible for molecular background of psoriasis." (PMID 30148172, 2018).
transitional cell carcinoma (2 papers, 2022 to 2024). A malignant neoplasm arising from the transitional epithelium, usually affecting the urinary bladder, ureter, or renal pelvis. "Similarly, this finding might be the reason for the strong negative correlation between COX-2 and PGP expression that we obtained in non-FISS, whereas recent studies have demonstrated the opposite correlation in canine transitional cell carcinoma." (PMID 39061572, 2024).
cyst (1 paper, 2014). A sac-like closed membranous structure that may be empty or contain fluid or amorphous material. "In the slides immunostained for PGP 9.5 and S-100, the presence of nerve fibers in the majority of cross-sections through the cyst wall was especially striking." (PMID 25044274, 2014).
leprosy (1 paper, 2012). Leprosy is a chronic infectious disease affecting primarily the skin and peripheral nervous system. "This work aimed to study the correlation between the degree of thermal sensitivity impairment measured by QST and the degree of denervation in leprosy skin lesions, evaluated by immunohistochemistry anti-PGP 9.5 and morphometry." (PMID 23272267, 2012).
pulmonary emphysema (1 paper, 2009). A subcategory of chronic obstructive pulmonary disease (COPD). "In support of this idea, PGP antagonists prevented the induction of pulmonary emphysema and right ventricular hypertrophy in mice caused by chronic administration of LPS." (PMID 19450278, 2009).
spinal cord tumor (1 paper, 2019). "We show that PgP can efficiently deliver pDNA encoding green fluorescence protein (pGFP) in rat glioblastoma (C6) cells in vitro and deliver pDNA encoding β-galactosidase protein (pβ-gal) in a rat spinal cord tumor model in vivo." (PMID 30965667, 2019). "Seven days later, the transfection efficiency of PgP/pβ-gal polyplexes in the spinal cord tumor was evaluated by x-gal staining." (PMID 30965667, 2019). "Our long-term goal is to develop PgP as a platform technology for delivery of therapeutic drugs and nucleic acids to spinal cord tumors." (PMID 30965667, 2019). "In vivo β-Gal expression was substantially higher in animals receiving PgP/pβ-Gal polyplexes compared with bPEI/pβ-Gal polyplexes in the rat spinal cord tumor model." (PMID 30965667, 2019). "In the future, we will evaluate the potential of PgP as a GCV and pHSV-TK co-delivery carrier to improve the bioavailability and half-life of GCV as well as increase the survival rate after treatment of PgP/pHSV-TK with PgP-GCV in rat T5 spinal cord tumor model." (PMID 30965667, 2019). "Finally, we show the suicide effect of PgP/pHSV-TK with GCV treatment in a rat T5 spinal cord tumor model." (PMID 30965667, 2019). "Finally, we evaluated the suicide effect of PgP/pHSV-TK with GCV in the rat spinal cord tumor model and observed that the percent tumor area in animals treated with PgP/pHSV-TK and GCV was significantly smaller than that of those receiving PgP/pHSV-TK polyplexes without GCV." (PMID 30965667, 2019). "Finally, we demonstrated that PgP/pHSV-TK with GCV treatment increases the suicide effect and apoptosis of tumor cells and reduces tumor size in a rat T5 spinal cord tumor model compared with PgP/pHSV-TK without GCV treatment." (PMID 30965667, 2019).
cancer (1,117 papers, 1996 to 2026). A tumor composed of atypical neoplastic, often pleomorphic cells that invade other tissues. "Overexpression of PgP and associated multidrug resistance was reported in cancer patients that are resistant to many anticancer agents." (PMID 22350019, 2012). "The P-glycoprotein (PgP) pump, a transmembrane protein responsible for immediate drug efflux from cancer cells, is one mechanism of BTZ resistance." (PMID 38072962, 2023). "MDR1 expression is often observed in cancer cells exposed to common chemotherapeutics that are substrates for PgP, which results in drug efflux and therapy failure." (PMID 35892900, 2022). "Variolin B had been shown to induce apoptosis exerting highly potent cytotoxic activity against various human cancer cell lines including the ones with overexpressed level of cell efflux pump p-glycoprotein (PGP)." (PMID 34440090, 2021). "We also observed that the anti-cancer efficacy of PgP/pHSV-TK polyplexes was significantly higher than that of bPEI/pGFP polyplexes (both with 100 μg/mL GCV) at 1 and 4 days post-treatment." (PMID 30965667, 2019). "The PgP/pHSV-TK transfected group with both GCV doses showed significantly higher anti-cancer efficacy compared to control groups including GCV only, PgP/pGFP only, and PgP/pHSV-TK without GCV treatment at both one and four days." (PMID 30965667, 2019). "Triple-immunofluorescent staining revealed significantly higher percentage of CASP8 and PGP 9.5 stained neurons in plexuses located distally from the tumor when compared to the cancer-affected stomach wall." (PMID 30019295, 2018). "Atorvastatin is an inhibitor of the human phosphoglycoprotein (PgP), an efflux protein involved in cancer cells." (PMID 24886347, 2014). "This is a remarkable result in the context of chemotherapy for drug-resistant cancers since the MESSA Dx5 cells contain an active PgP efflux pump." (PMID 23505430, 2013). "AMG-900 was able to overcome the resistance particularly in PgP upregulated multidrug resistant cancer cell lines." (PMID 22350019, 2012). "One of the common mechanism of cancer cell drug resistance is the overexpression of PgP, which actively effluxes the anticancer agent before reaching the target." (PMID 22350019, 2012). "The glycoprotein transporter known as PGP modulates the rate of drug penetration into cancer cells." (PMID 39003454, 2024). "PgP is a well-known molecule that mediates drug resistance in different types of cancers." (PMID 38072962, 2023). "In addition, we also checked the PGP protein that is related to drug efflux in case of cancer cells and is normally active to efflux out the drugs taken in by cells in defense response." (PMID 35982963, 2022). "Comparable to our observations in cancer cell lines, human fibroblasts with complete PGP knockout show 25-fold, 9-fold and 110-fold increases in 2-P-lactate, 4-P-erythronate and 6-P-gluconate, respectively, whereas phosphoglycolate and 3-P-glycerol levels remain unchanged or are reduced." (PMID 30670572, 2019). "Interestingly it was able to overcome the resistance in PgP (P-glycoprotein) expressing multidrug resistant cancer cell lines, as it inhibited colony formation of resistant and parent cell lines uniformly." (PMID 22350019, 2012). "It is possible to speculate that high PGP expression in NSCLC may imply a more aggressive clinical behavior of cancer cells." (PMID 19662216, 2007). "The anti-cancer efficacy of PgP/pHSV-TK polyplexes with both GCV doses of 50 and 100 μg/mL was significantly higher than that of PgP/pGFP polyplexes at both 1 and 4 days post-treatment." (PMID 30965667, 2019). "MDR1/PgP acts as a glycolipid translocase involved in the biosynthesis of glycolipids such as Gb3, and elevated levels of Gb3 have also been seen in drug-resistant cancers, and functional interplay between membrane Gb3 and MDR1/PgP has been suggested." (PMID 20010943, 2010).